Y_RNA (Y RNA )
Gene: Miscellaneous RNA gene on chromosome 2 (201,423,513 to 201,423,604, forward strand). Ensembl gene ENSG00000202008.
Homologues: Orthologues: chimpanzee Y_RNA (100% identical). Paralogues in human: Y_RNA (89% identical), RNY4 (86% identical), Y_RNA (84% identical), RNY4P6 (83% identical), Y_RNA (83% identical), RNY4P10 (82% identical), RNY4P14 (82% identical), RNY4P23 (82% identical), RNY4P3 (82% identical), RNY4P34 (82% identical), RNY4P7 (82% identical), Y_RNA (82% identical), and 87 more.